SOD1 (superoxide dismutase 1)
Diseases named in the same sentence as SOD1 in open-access papers (continued):
Sharing a sentence is not in itself a finding about the gene and the disease.
spinal muscular atrophy (17 papers, 2013 to 2025). A motor neuron disease that affect the muscles, and characterized by muscle weakness and atrophy resulting from progressive degeneration and irreversible loss of the anterior horn cells in the spinal cord (i.e., lower motor neurons) and the brain stem nuclei. "A recent study in smn based spinal muscular atrophy (SMA) shows that SOD1 can alter the bouton morphology caused because of smn knock down." (PMID 25361581, 2014). "Both nusinersen and tofersen, approved ASO drugs for the treatment of spinal muscular atrophy and SOD1-driven ALS, respectively, are administered directly to the CNS through intrathecal infusions." (PMID 38613388, 2024). "These are, however, sequence-dependent effects, and, through screening and development, safe and effective ASO medicines have been developed, as exemplified by nusinersen for spinal muscular atrophy and tofersen for SOD1-dependent ALS." (PMID 38357922, 2024). "ASO treatment for spinal muscular atrophy was recently approved following successful clinical trials and ASOs are also in clinical trial for SOD1 ALS." (PMID 30496365, 2018). "Previous animal work has identified an increased expression of miR-206 over time in the ALS SOD1 G93A mouse model and the murine spinal muscular atrophy model, correlating with increasing pathology and associated muscle denervation." (PMID 28454844, 2017). "Third, Stathmin accumulation represents a pathologically relevant feature shared between SOD1-linked ALS and mutant SMN-linked spinal muscular atrophy (SMA)." (PMID 27277231, 2016).
liver cancer (16 papers, 2013 to 2026). An epithelial or non-epithelial malignant neoplasm that arises from the liver. "A previous report indicates that Sod1 deficiency leads to the development of liver cancer at late age of mice (∼20 months), which might attribute to persistent oxidative damage to DNA in livers." (PMID 40690812, 2025). "Sod1-deficient mice develop liver cancer, as marked by extensive oxidative and DNA damage." (PMID 37898799, 2023). "This suggests that the loss of c-Met/HGF signaling, accompanied by a loss of antioxidants such as superoxide dismutase (SOD1) and NRF2, and its down regulation led to enhancement of liver tumor growth in the c-myc model of liver cancer by promoting a more favorable environment for cancerous growth." (PMID 40149719, 2025). "A study revealed that notopterol downregulated the expression levels of p-JAK2, ATF4, glutathione peroxidase 1 (GPX1), catalase (CAT), and superoxide dismutase 1(SOD1) proteins in liver cancer cell lines, thereby reducing the proliferation and invasion capabilities of cancer cells." (PMID 39770441, 2024). "Conclusions: the persistent upregulation of c-Myc in the ATT-Myc liver cancer model, at both the gene and protein levels following DEN treatment inhibited the ETS1 transcription factor, further exacerbating the decline of c-Met signaling, SOD1, and NRF2." (PMID 40149719, 2025). "This function has been shown in SOD1-knockout mice, where the absence of SOD1 increased oxidative stress and led first to liver cell damage and eventually liver cancer." (PMID 38218941, 2024).
mastitis (16 papers, 2015 to 2025). Inflammation of breast tissue during lactation or postpartum due to an obstructed duct or infection. "As far as we are concerned, this is the first study revealing SNPs in SELL, ABCG2, SLC11A1, FEZL, SOD1, CAT, GPX1, and AhpC/TSA genes as candidates for mastitis tolerance/susceptibility in Holstein and Brown Swiss dairy cows." (PMID 35737346, 2022). "In the present study, a real-time PCR was carried out to quantify the mRNA level of SELL, ABCG2, SLC11A1, FEZL, SOD1, CAT, GPX1, and AhpC/TSA genes in tolerant and susceptible Holstein and Brown Swiss dairy cows to mastitis." (PMID 35737346, 2022). "PCR-DNA sequencing of SELL, ABCG2, SLC11A1, FEZL, SOD1, CAT, GPX1, and AhpC/TSA revealed nucleotide sequence variations in the form of SNPs associated with mastitis tolerance/susceptibility in investigated Holstein and Brown Swiss dairy cows." (PMID 35737346, 2022). "In this study, another homologous protein SOD1 with high expression was also discovered in sheep mammary glands with clinical mastitis." (PMID 31159303, 2019). "Consequently, the aim of the current work was to revealing the association of SNPs and expression profile of SELL, ABCG2, SLC11A1, FEZL,SOD1,CAT,GPX1, and AhpC/TSA genes with mastitis tolerance/susceptibility in Holstein and Brown Swiss dairy cows." (PMID 35737346, 2022). "The current study showed that bovine neutrophil exposure to minor mastitis-causing bacteria resulted in the upregulation of genes associated with key components involved in ROS generation, with a specific focus on NOX1, CYBA (p22phox), and SOD1 potentially playing a prominent role in this response." (PMID 38922009, 2024). "Consequently, SELL, ABCG2, SLC11A1, FEZL, SOD1, CAT, GPX1, and AhpC/TSA regulation mechanisms are well understood in the mastitis tolerant and affected Holstein and Brown Swiss dairy cows." (PMID 35737346, 2022).
parasitemia (16 papers, 2014 to 2025). "E8.5 infected mice had elevated transcripts for Ifnγ, Tnf, Il10, Cox1, Cox2, Sod1, Sod2, Cat, and Nrf2, while Sod3 was the only transcript that correlated with parasitemia." (PMID 35312688, 2022). "Interestingly, the expression of SOD1 protein in the heart significantly decreased after parasite infection and increased after the chronic phase." (PMID 37623985, 2023). "Conversely, the increase in parasitemia observed for SOD1 KO mice might have been due to impairment of formation of H2O2 or other ROS that might affect parasite survival in vivo." (PMID 24586264, 2014).
type 1 diabetes (16 papers, 2012 to 2025). "We assessed all models by analyzing WGA-stained skeletal muscle images from wild-type and disease models (G93A*SOD1 for ALS and Akita for type 1 diabetes)." (PMID 40671798, 2025). "This system significantly improved the morphology, viability and function of the incubated NPCCs, and the slow SOD1 release could contribute to overcome the scarcity of transplant in patients with type 1 diabetes mellitus (T1DM)." (PMID 33321882, 2020).
autism (15 papers, 2013 to 2025). Persistent deficits in social interaction and communication and interaction as well as a markedly restricted repertoire of activity and interest as well as repetitive patterns of behavior. "Interestingly, while most neurodegeneration-related risk genes, such as APP and SOD1, are usually associated with a specific disease, GRN mutations and polymorphisms appear to be involved in a diverse group of neurological conditions, ranging from FTLD to ALS, AD, PD and even autism." (PMID 36009452, 2022). "However, adult B6 mice exposed to methylmercury chloride during the juvenile period showed an upregulation of the Nrf2 signaling pathway and HO-1/SOD-1 antioxidant enzymes which could be responsible for the lack of development of autism-like behavior in these mice." (PMID 37368646, 2023).
emphysema (14 papers, 2013 to 2025). "DMF treatment at both 30 mg/kg and 100 mg/kg doses prevented the reduction in SOD1 expression during PPE-induced emphysema development." (PMID 41009045, 2025).
glioblastoma (14 papers, 2016 to 2026). The most malignant astrocytic tumor (WHO grade IV). "A decrease in SOD1 expression has been identified in glioblastomas and is associated with improved response to radiotherapy and a better prognosis for patients." (PMID 36142793, 2022). "Evaluating SOD1 inhibitors like ATN-224 alongside mTORC1 inhibitors in glioblastoma should prioritize identifying responsive tumor subtypes." (PMID 41009046, 2025). "TAp73 deficiency was reported to exacerbate glutamine dependence by decreasing superoxide dismutase 1 (SOD1) expression, thereby enhancing ROS accumulation, and increasing autophagy, thus significantly reducing glioblastoma self-renewal capacity." (PMID 37422448, 2023). "Finally, in glioblastoma under dual nutrient/oxygen stress, mTORC1 inhibition (via rapamycin) unleashes SOD1’s detoxifying power, safeguarding tumor cells from ROS-induced death; by contrast, TSC2 knockdown activates mTORC1 and reduces SOD1 activity under starvation." (PMID 41009046, 2025). "Moreover, CLO inhibits growth and inhibits genes related to OS defense (thioredoxin peroxidase, glutaredoxin, nitric oxide oxidoreductase, cytochrome c peroxidase and b5 reductase, GPx, SOD1, SOD2, and CAT) in glioblastoma patient biopsy-derived cell cultures." (PMID 41154163, 2025). "Biological testing confirmed the ability of 1 to induce a mixed, non-lethal stress response in human U87-MG glioblastoma cells; analysis of stress markers by qRT-PCR revealed early upregulation of superoxide dismutase 1 (SOD1) and C/EBP-homologous protein (CHOP) relative to the control." (PMID 42080225, 2026).
infarction (14 papers, 2013 to 2025). A localised pathological necrosis of tissue resulting from obstruction of the blood supply usually by a thrombus, an embolus, or vascular torsion. "The combined data from the two groups are well fit with a single function, consistent with a decrease in the level of CuZn–SOD in Sod1+/− mice exacerbating both infarction and swelling in a proportional manner, with no independent effect on brain swelling." (PMID 38539619, 2024).
non-small cell lung carcinoma (14 papers, 2013 to 2024). A group of at least three distinct histological types of lung cancer, including non-small cell squamous cell carcinoma, adenocarcinoma, and large cell carcinoma. "Up to now, we do not have a clear explanation of this phenomenon, however, the correlation of the overexpression of naive SOD1 has been documented in the non-small cell lung cancer where the rate of proliferation was associated with the activity of miR-409-3p/SOD1/SETDB1 pathways." (PMID 34572266, 2021). "The results of our study suggested that the anti-growth potential of exogenous long carbon-chain C8-ceramide against human non-small-cell lung cancer cells may occur through the modulation of the ratio of SOD1 and SOD2." (PMID 30279365, 2018). "In specific circumstances, copper-induced oxidative stress can be reduced, and/or ribosome biogenesis can be enhanced to promote tumorigenesis by elevated levels of SOD1, as demonstrated in mouse models of HER2-positive BC and KrasG12D-mutant non-small cell lung cancer (NSCLC)." (PMID 39482784, 2024). "In non-small-cell lung cancer (NSCLCs), SOD1 (superoxide dismutase 1) is expressed at high levels." (PMID 28808499, 2017).
oral cancer (14 papers, 2019 to 2024). "Western blotting revealed that silibinin downregulated SOD1 and SOD2 and triggered the JNK/c-Jun pathway in oral cancer cells." (PMID 37476191, 2023). "Pomegranate extract also downregulates NFE2L2, TXN, CAT, SOD1, and HMOX1 gene expressions in oral cancer cells and induces oxidative stress." (PMID 36139851, 2022). "In the current study, antioxidant gene expressions (NFE2L2, SOD1, TXN, GSR, CAT, and GPX1) in oral cancer Ca9-22 and CAL 27 cells were highly downregulated by UVC/sinularin combined treatments compared to the separate treatments." (PMID 34070049, 2021). "Accordingly, the antioxidant signaling gene expression for mRNA, including NFE2L2, GCLC, TXN, CAT, SOD1, HMOX1, and NQO1, was examined for POMx-incubated oral cancer cells." (PMID 34356350, 2021). "Similar to the present study, the mRNA expressions for several antioxidant genes (NFE2L2, GCLC, TXN, CAT, SOD1, HMOX1, and NQO1) were downregulated at 24 h POMx for three oral cancer cell lines." (PMID 34356350, 2021). "Accordingly, the gene expressions of antioxidant genes such as NFE2L2, SOD1, TXN, GSR, CAT, and GPX1 were evaluated by qRT-PCR following UVC and/or sinularin treatments in oral cancer cells (Ca9-22 and CAL 27)." (PMID 34070049, 2021).
endotoxemia (13 papers, 2013 to 2025). "Sod1 was reported to regulate caspase-1 activaton and endotoxic shock; Sod1-deficient mice were less susceptible to LPS induced endotoxemia." (PMID 31766320, 2019).
Hepatitis (13 papers, 2008 to 2026). Inflammation of the liver. "In either case we observed increased hepatitis in Sod1−/− mice compared to WT mice, suggesting that the pathology is independent of the infection inoculum and LCMV strain." (PMID 26588782, 2015). "The association between SOD1 (Cu2+/Zn2+-dependent superoxide dismutase) and CCL5 in the nervous system has not been reported; to date, such a relationship has only been identified in the context of hepatitis." (PMID 41508046, 2026). "We also measured two alternative parameters for hepatitis, aspartate aminotransferase (AST) and alkaline phosphatase (AP), and found elevated concentrations in Sod1−/− compared to WT mice." (PMID 26588782, 2015). "Importantly, rIFN-α led to increased expression of Atf3 mRNA and was sufficient to induce hepatitis as measured by ALT in Sod1−/− mice in the absence of infection." (PMID 26588782, 2015).
renal failure (13 papers, 1998 to 2026). "In contrast, despite preservation of NRF2 signaling in calcified epigastric arteries from kidney failure patients, its target SOD1 was decreased, potentially participating in the established vessel calcification." (PMID 36831311, 2023).
retinal degeneration (13 papers, 2016 to 2024). Degeneration of the retina. "Finally, to assess whether Myriocin (or any derivative metabolites) could act via signaling pathways known to act in inherited retinal degeneration, we analyzed retinal protein levels of Sod1, one of the main enzymes of the physiological anti-oxidant system." (PMID 32435178, 2020). "VEGF-B protects retinal cells against oxidative stress and rescues retinal degeneration by upregulating the antioxidative genes GPX1 and SOD1." (PMID 34631708, 2021). "It is interesting that Catalase expression correlates with protection against blue light stress because overexpression of Superoxide dismutase 1 (Sod1) decreases H2O2 levels in the eye but does not protect against blue light-induced retinal degeneration." (PMID 35205309, 2022).
chronic obstructive pulmonary disease (12 papers, 2013 to 2025). A chronic and progressive lung disorder characterized by the loss of elasticity of the bronchial tree and the air sacs, destruction of the air sacs wall, thickening of the bronchial wall, and mucous accumulation in the bronchial tree. "Similar to the effects of catalase, PC-specific overexpression of both the cytosolic and mitochondrial isoforms of SOD (SOD1 and SOD2) increased the incidence of cardiac arrhythmia and caused constriction of the heart tube." (PMID 24656823, 2014). "Co-expression of UNC-45 and SOD-1 restored cardiac contractility and suppressed cardiac dilation, as well as cardiac arrhythmias." (PMID 24367279, 2013).
diabetic cardiomyopathy (12 papers, 2013 to 2025). Diabetic cardiomyopathy is a disorder of the heart muscle in people with diabetes. "In experimental diabetic cardiomyopathy models, trientine has been demonstrated to increase superoxide dismutase-1 (cytosolic SOD1) and superoxide dismutase-3 (SOD3, also known as extracellular SOD and EC-SOD) expression." (PMID 36145368, 2022).
varicocele (12 papers, 2015 to 2024). A condition characterized by the dilated tortuous veins of the spermatic cord with a marked left-sided predominance. "Further, western blot (WB) analysis revealed SOD1 was significantly underexpressed (p = 0.0143) in the bilateral varicocele group." (PMID 32365753, 2020). "WB analysis of immunoprecipitated SOD1 protein present in the network confirms that the proteins identified as acetylated proteins undergo PTM in the spermatozoa of varicocele patients." (PMID 32365753, 2020). "Therefore, the differential acetylation of SOD1 in both groups might be due to differences in the incidence of oxidative stress as both the testes in bilateral varicocele experience hypoxia, while in unilateral varicocele, the contra-lateral testis has normal blood flow." (PMID 32365753, 2020). "Some of the DEP in unilateral varicocele group including PRDX1, SOD1, SOD2 were shown to be involved in the removal of superoxide." (PMID 25890347, 2015). "In addition, the acetylation status of proteins, such as HIST1H2B, PRDX1, SDHA, and SOD1, can serve as a biomarker for PTM defects pertaining to the acetylation process in the ejaculated spermatozoa of varicocele patients." (PMID 32365753, 2020).
Arrhythmia (11 papers, 2013 to 2025). Any cardiac rhythm other than the normal sinus rhythm. "This supports our results that SOD2 KD shows increased CaT loss and contractile dysfunction compared to SOD1 in iAMS and only SOD2 KD, but not SOD1 KD, induced arrhythmia in Drosophila." (PMID 41462644, 2025). "Interestingly, SOD2, but not SOD1, heart-specific and whole-body knockdown increased arrhythmia, validating the in vitro finding that MitoOxS specifically induces cardiac dysfunction." (PMID 41462644, 2025).
Ataxia (11 papers, 2014 to 2025). Ataxia refers to impaired coordination of voluntary muscle movement. "Coexistence with cerebellar ataxia may suggest the involvement of mutations of SOD1, ATXN2, Alsin, and SETX." (PMID 26213621, 2015). "Extensive genetic testing has been performed in various cases, which included ALS genes (C9orf72, FUS, SOD1, TARDBP), oculopharyngeal muscular dystrophy (PABPN1), Kennedy disease (AR), panels for spinocerebellar ataxia as well as whole-exome sequencing." (PMID 33842068, 2021). "In addition, SPG11 and FUS can be sequenced in cases who also present mental retardation, while SOD1, Alsin, SETX, ATXN2 can be considered in those cases with coexistence of cerebellar ataxia." (PMID 26843957, 2016).
cervical carcinoma (11 papers, 2005 to 2024). A carcinoma arising from either the exocervical squamous epithelium or the endocervical glandular epithelium. "Some oxidative stress-related proteins have been reported in EVs of cervical cancer, such as the cytochrome P450 family proteins CYP1A1, CYP1B, and CYP2A6, as well as the antioxidant enzyme superoxide dismutase 1 (SOD1)." (PMID 34202942, 2021). "Activation of LPA3 with its highly selective agonist, OMPT, showed potent induction of mitochondrial antioxidants, glutathione peroxidase 1 (Gpx1), and superoxide dismutase type 1 and type 2 (SOD1 and SOD2) protein expression in human cervical cancer HeLa cells." (PMID 35204233, 2022).
acute pancreatitis (10 papers, 2013 to 2025). An acute inflammatory process that leads to necrosis of the pancreatic parenchyma. "This study aimed to evaluate changes in IL-6 concentration and the concentration/activity of superoxide dismutase isoenzymes (SOD1, SOD2, and SOD3) in the blood of patients with acute pancreatitis (AP) in terms of rs1800795 polymorphism in the IL6 gene." (PMID 35205334, 2022). "Acute pancreatitis is accompanied by an increased antioxidant defense as evidenced by the increase in plasma SOD1 concentration." (PMID 35205334, 2022). "This study was aimed at evaluating the impact of acute pancreatitis on the changes in concentration and activity of all three superoxide dismutase isoenzymes: cytosolic SOD1, mitochondrial SOD2 and extracellular SOD3 in extracellular (plasma) and intracellular (erythrocyte lysate) compartments." (PMID 33019780, 2020).